ZNF599 (zinc finger protein 599)
Description:
May be involved in transcriptional regulation.
Synonyms: FLJ30663
Tractability: Antibody: the Human Protein Atlas places it where antibodies can reach. PROTAC: ubiquitination databases record sites on it.
Gene: Protein-coding gene on chromosome 19 (34,758,073 to 34,773,229, reverse strand). Ensembl gene ENSG00000153896.
Subcellular location: Nucleus
Subcellular location (Human Protein Atlas): Cytosol; Plasma membrane; Nucleoplasm
Pathways (Reactome):
Gene expression (Transcription): Generic Transcription Pathway
Gene Ontology:
Molecular function: protein binding; DNA-binding transcription factor activity, RNA polymerase II-specific; RNA polymerase II transcription regulatory region sequence-specific DNA binding
Biological process: regulation of transcription by RNA polymerase II; regulation of DNA-templated transcription
Cellular component: nucleus
Genetic constraint (gnomAD): Loss-of-function variants: 12 observed, 11.76 expected, observed/expected ratio (o/e) 1.02, 90% interval 0.65 to 1.63. The upper end of that interval is the gene's LOEUF score, 1.63, which puts it in group 6 of 6, group 1 being the genes least tolerant of losing a copy. Missense variants: 687 observed, 746.25 expected, observed/expected ratio (o/e) 0.92, 90% interval 0.86 to 0.98. Synonymous variants: 232 observed, 264.41 expected, observed/expected ratio (o/e) 0.88, 90% interval 0.79 to 0.98.
Homologues: Orthologues: chimpanzee ZNF599 (99% identical), macaque ZNF599 (96% identical), pig ZNF599 (88% identical), dog ZNF599 (87% identical), guinea pig ZNF599 (71% identical), Drosophila melanogaster CG3281 (22% identical), Drosophila melanogaster CG2712 (22% identical), Drosophila melanogaster Phs (19% identical). Paralogues in human: ZNF805 (58% identical), ZNF264 (55% identical), ZNF550 (44% identical), ZNF555 (39% identical), ZNF266 (39% identical), ZFP37 (38% identical), ZNF582 (37% identical), ZFP90 (37% identical), ZNF778 (37% identical), ZNF133 (36% identical), ZNF404 (36% identical), ZNF169 (35% identical), and 50 more.